SSR3 (signal sequence receptor subunit 3)
Description:
TRAP proteins are part of a complex whose function is to bind calcium to the ER membrane and thereby regulate the retention of ER resident proteins.
Synonyms: TRAPG
Tractability: Antibody: UniProt predicts a signal peptide or a membrane-spanning region. PROTAC: ubiquitination databases record sites on it; its protein half-life has been measured.
Gene: Protein-coding gene on chromosome 3 (156,539,553 to 156,559,474, reverse strand). Ensembl gene ENSG00000114850.
Subcellular location: Endoplasmic reticulum membrane
Pathways (Reactome):
Metabolism of proteins: SRP-dependent cotranslational protein targeting to membrane
Gene Ontology:
Molecular function: protein binding
Biological process: post-translational protein targeting to membrane, translocation; SRP-dependent cotranslational protein targeting to membrane
Cellular component: endoplasmic reticulum; endoplasmic reticulum membrane; translocon complex; membrane
Genetic constraint (gnomAD): Loss-of-function variants: 10 observed, 20.77 expected, observed/expected ratio (o/e) 0.48, 90% interval 0.3 to 0.82. The upper end of that interval is the gene's LOEUF score, 0.82, which puts it in group 3 of 6, group 1 being the genes least tolerant of losing a copy. Missense variants: 180 observed, 224.19 expected, observed/expected ratio (o/e) 0.8, 90% interval 0.71 to 0.91. Synonymous variants: 104 observed, 85.13 expected, observed/expected ratio (o/e) 1.22, 90% interval 1.04 to 1.44.
Homologues: Orthologues: chimpanzee SSR3 (100% identical), macaque SSR3 (100% identical), mouse Ssr3 (99% identical), pig SSR3 (99% identical), rat Ssr3 (99% identical), guinea pig SSR3 (98% identical), tropical clawed frog ssr3 (95% identical), zebrafish ssr3 (95% identical), rabbit SSR3 (87% identical), Drosophila melanogaster CG5885 (64% identical), dog SSR3 (54% identical), Caenorhabditis elegans trap-3 (39% identical).
Diseases named in the same sentence as SSR3 in open-access papers:
SSR3 is named in the same sentence as 11 diseases in open-access papers, as found by Europe PMC text mining. Sharing a sentence is not in itself a finding about the gene and the disease. The quoted sentences say what the papers report.
breast carcinoma (4 papers, 2019 to 2024). "SSR3 KO in PTX-sensitive breast cancer (MDA-MB-468) and glioma H4 cells resulted in resistance to PTX." (PMID 38329732, 2024). "A probe named as cg24921140 detected the 3’UTR region of SSR3, implying the specific expression alteration of such gene in different subtypes of breast cancer." (PMID 31480430, 2019). "A negative correlation was found between higher SSR3 expression and PTX resistance in GBM and breast cancer cell lines." (PMID 38329732, 2024).
glioma (2 papers, 2024). A benign or malignant brain and spinal cord tumor that arises from glial cells (astrocytes, oligodendrocytes, ependymal cells). "We discovered a positive correlation between SSR3 expression and IRE1a levels in glioma PDX cells." (PMID 38329732, 2024).
congenital disorder of glycosylation (1 paper, 2021). Congenital disorder of glycosylation (CDG) is a fast growing group of inborn errors of metabolism characterized by defective activity of enzymes that participate in glycosylation (modification of proteins and other macromolecules by adding and processing of oligosaccharide side chains). "Third, only one of the negatively affected peroxisomal proteins, PEX13, had previously been observed for TRAP-deficient fibroblasts from patients who suffer from congenital disorders of glycosylation (CDG) and are either SSR3- (coding for TRAPγ) or SSR4 (TRAPδ)-deficient." (PMID 34884833, 2021).
esophageal squamous cell carcinoma (1 paper, 2017). Esophageal squamous cell carcinoma (ESCC) is a type of esophageal carcinoma (EC) that can affect any part of the esophagus, but is usually located in the upper or middle third. "SSR3 was also identified as a novel candidate oncogene that showed different amplification patterns among different genes within 3q25·3-qter in esophageal squamous cell carcinoma." (PMID 29108335, 2017).
melanoma (1 paper, 2025). A malignant, usually aggressive tumor composed of atypical, neoplastic melanocytes. "Consistent with our in vitro findings, genes associated with the ATF4 (e.g., ATF4, DDIT3, PPP1R15A and CHAC1), ATF6 (e.g., ATF6B, CALR, SEL1L, and EDEM1) and XBP1 (e.g., SSR3 and DELR1) pathways were significantly enriched in melanoma TILs compared with healthy blood T cells." (PMID 40335738, 2025).
tumor (5 papers, 2020 to 2025). "ER signal sequence receptor subunit: SSR3 that regulates protein entry into ER plays a major role in protein processing in ER and its dysregulation has been found associated with tumor growth in PCa." (PMID 33572476, 2021). "Of all the undeleted genes, SSR3 (a member of signal sequence receptor family) is heavily involved in cell growth and differentiation and closely associated with many tumor types." (PMID 33120794, 2020). "SSR3 is highly expressed in HCC and is associated with tumor size, TNM stage, differentiation grade, and poor prognosis." (PMID 36211823, 2022).
carcinoma (1 paper, 2021). A malignant tumor arising from epithelial cells. "According to our experiments, the difference expression of SSR-3 in carcinoma and adjacent tissues was the most significant, so the involvement in migration and invasion processes was investigated for SSR3-6." (PMID 34150667, 2021).
SSR3 also shares sentences with these, for which no sentence is quoted: bladder cancer (1 paper); hematological disorders (1); hepatocellular carcinoma (1); myeloid neoplasm (1).